Y_RNA (Y RNA )
Gene: Miscellaneous RNA gene on chromosome 15 (64,652,888 to 64,652,989, forward strand). Ensembl gene ENSG00000207223.
Homologues: Orthologues: chimpanzee Y_RNA (99% identical), macaque Y_RNA (95% identical), guinea pig Y_RNA (90% identical), guinea pig Y_RNA (89% identical). Paralogues in human: RNY3P1 (90% identical), Y_RNA (90% identical), RNY3 (89% identical), Y_RNA (89% identical), Y_RNA (88% identical), Y_RNA (87% identical), Y_RNA (86% identical), RNY3P14 (85% identical), Y_RNA (85% identical), Y_RNA (84% identical), RNY3P11 (83% identical), RNY3P16 (83% identical), and 97 more.